HNF4A (hepatocyte nuclear factor 4 alpha)
Diseases named in the same sentence as HNF4A in open-access papers (continued):
Sharing a sentence is not in itself a finding about the gene and the disease.
tumor (continued). "It has been previously demonstrated that the TP63/TP53L, ERG, GRHL1/Get-, HNF1A/TCF-1, SPI1/PU.1, WT1 and GLIS2, FOXM1 and FOXP3 transcription factor networks, which are mediated by HNF4A, can regulate the expression of Trop2 in tumor tissues." (PMID 25779928, 2015). "A number of these genes (including PIK3R3, a member of the PI3K pathway, and PKLR, an isoform of pyruvate kinase) showed exceptionally strong co-expression with HNF4A in normal samples, only to have this co-expression abrogated in tumor samples." (PMID 25961905, 2015). "Although frequently described as a tumour-suppressor gene, HNF4A plays a role in cancer initiation and intracellular protection against cancer-related ROS production." (PMID 24728830, 2014). "Both HNF4α and miR-122 act as tumor suppressors and negative regulators of HCC invasion and metastasis, whereas RhoA positively regulates HCC invasion and metastasis." (PMID 24992599, 2014). "This network also exhibited focus hubs containing NFκB, ERK1/2, UBC, p38MAPK, and HNF4α, all which regulate inflammation, and survival and proliferation of tumor cells." (PMID 24283668, 2013). "The merged interactomes of Networks 3 and 5 generated a distinct hub around hepatocyte nuclear transcription factor 4 alpha (HNF4A), suggesting its involvement in tumor metabolism and transcriptional regulation." (PMID 22848702, 2012). "Ectopic HNF4α-expression reduces proliferation in HEK293 cells (a human embryonic kidney cell line) and therefore, the authors postulate a possible tumour suppressor activity of HNF4α." (PMID 21244694, 2011). "It has also been reported that HNF4α is downregulated in other types of tumours and that it induces expression of endothelial Fas ligand (FasL), which prevents cancer cell transmigration." (PMID 16479257, 2006). "Rather than acting as a classical oncogene or tumor suppressor in all settings, HNF4α is better understood as a context-dependent regulator of lineage state whose activity may either restrain tumor progression or support tumor maintenance." (PMID 41925866, 2026). "In cancer, HNF4α can function as either an oncogene or a tumor suppressor." (PMID 41925866, 2026). "HNF4α performs a tumor suppressor function in prostate cancer and in PAAD." (PMID 40277924, 2025). "Restoring tumour suppressors such as HNF4A and RASSF1 could further improve outcomes, though this remains an area of active research." (PMID 41007296, 2025). "Together with evidence that HNF4α regulates more than two thousand genes, as demonstrated by global transcriptomic analyses following its silencing in cultured hepatocytes or in animal models, these findings establish HNF4α as a master regulator of hepatocyte identity and a tumor suppressor." (PMID 41595461, 2025). "In contrast, HNF4A, RASSF1, SPARCL1, and LHPP are associated with favourable outcomes: HNF4A regulates hepatocyte differentiation, RASSF1 acts as a tumour suppressor, SPARCL1 inhibits angiogenesis and metastasis, and LHPP suppresses tumour growth." (PMID 41007296, 2025). "Another HNF4α-induced epi-miRNA with tumor suppressive activity in HCC progression is miR-124." (PMID 41595461, 2025). "After labeling the corresponding cells with specific antibodies (PSMA for LNCaP95, HNF4α for hepatocytes, and F4/80 for macrophages, primarily Kupffer cells), we observed a remarkable accumulation of mCherry protein predominantly in LNCaP95 tumor cells." (PMID 40349174, 2025). "Interestingly, mice inoculated with PANC-1 GFP cells developed palpable tumours 1 week post cell engraftment, whereas in the ones inoculated with PANC-1 HNF4A, the same number of cells produce tumours 3 weeks post cell engraftment." (PMID 39165427, 2024). "Also, the tumor-promoting role of HNF4α through induction of cell proliferation, invasion, metastasis and angiogenesis is well studied." (PMID 39199690, 2024).
tumor (continued). "Clinicopathological analysis revealed that HNF4A staining is associated with tumour stage and not with a variety of other clinicopathologic variables, such as gender, tumour size, and age." (PMID 39165427, 2024). "Therefore, HNF4α has the ability to reverse tumor lesions by inhibiting the activation of the STAT3 signaling pathway and suppressing the invasion and metastasis of cancer cells." (PMID 38372868, 2024). "HNF4A is a key transcription factor in gastrointestinal epithelium, which suggests that tumor cells may transdifferentiate in this region." (PMID 39639005, 2024). "The potential role of the IPMN tumor-microenvironment in HNF4α modulation has yet to be studied." (PMID 37974020, 2023). "HNF4α expression may be negatively correlated with tumor growth, and its overexpression may inhibit liver cancer growth." (PMID 36647780, 2023). "Moreover, instead of FOXA1, these HNF4A+ tumor-specific hypoDMRs were co-enriched for AP-1 factors, which are well-recognized for their function in promoting EAC malignancy, similar to HNF4A itself." (PMID 37620896, 2023). "Further research is still needed to determine how HNF4A affects ferroptosis in various tumor types." (PMID 37180584, 2023). "Modulation of tumor differentiation may be attributed to HNF4α-mediated inhibition of mesodermal lineage markers SIX1 and SIX4 that are activated in the basal molecular subtype of PDAC21." (PMID 37974020, 2023). "Importantly, we functionally validated that FOSL1 and HNF4A cooperatively bind to a subset of tumor-specific hypoDMRs." (PMID 37620896, 2023). "The IHC in a mouse tumor xenograft further verified that HNF4A could inhibit the activity of the Wnt/β-catenin pathway." (PMID 35132353, 2022). "Noteworthy, focal aggregates of cohesively appearing HNF4α positive cells consistent with foci of re-differentiated tumor cells could be detected within HLN (center, insert showing a detailed view)." (PMID 36209041, 2022). "HNF4A is a known tumor suppressor, regulating the transcription of a myriad of genes." (PMID 35327967, 2022). "For HNF4A (Hepatocyte Nuclear Factor 4, Alpha), a tumor suppressor, its expression could affect the prognosis of KIRC." (PMID 35832648, 2022). "Xenograft assays suggested that HNF4A inhibited tumor formation and tumor growth in vivo." (PMID 35132353, 2022). "Furthermore, metformin downregulates hepatocyte nuclear factor 4 alpha (HNF4α) by activating AMPKα, leading to cyclin downregulation, cell cycle arrest, and tumor growth inhibition." (PMID 36430639, 2022). "Nevertheless, remaining tissues on tumor rims still expressed HNF4α." (PMID 35343115, 2022). "HNF4α function as a tumor suppressor in clear cell renal cell carcinoma (ccRCC)." (PMID 36249028, 2022). "One class of serum metabolites with highest abundance, namely acylcarnitines, is strongly correlated with tissue metabolites and reflect the pathway analysis based on tumor and adjacent non-tumor matched tissue gene expression, with HNF4α as possible transcriptional regulator." (PMID 34103600, 2021). "In gastric carcinogenesis, both P1- and P2-HNF4A were positive in gastric precancerous lesions and tumor tissues, which suggests that the HNF4A gene may exhibit oncogenic activity in GC." (PMID 33710810, 2021). "Finally, data in the GEPIA database also revealed significantly higher HNF4A expression levels in tumor tissues than in non-tumor tissues." (PMID 33710810, 2021). "Many studies have ascribed a tumor suppressor role to HNF4α in CRC." (PMID 34771521, 2021).
tumor (continued). "However, other published reports have also suggested the tumor promoter effects of HNF4α, depending on the tissue and the isoform of HNF4α expressed in the specific tissue." (PMID 34771521, 2021). "TGFβ overrides the tumor-suppressive activity of HNF4α through the inactivation of GSK3β." (PMID 33462379, 2021). "Therefore, HNF4α can alleviate or reverse tumor lesions by blocking the activation of the STAT3 signal transduction pathway and inhibiting the invasion and metastasis of cancer cells." (PMID 33462379, 2021). "Abnormal expression of HNF4α appears to be involved in cell proliferation, invasion and metastasis in some cancers, but may suppress tumor growth in other cancers." (PMID 33462379, 2021). "The presence of TGFβ impairs the efficiency of HNF4α as a tumor suppressor." (PMID 33462379, 2021). "By regulating these proliferation regulatory genes, HNF4A works as a tumor suppressor." (PMID 33778495, 2021). "It has been found that HNF4α has either oncogenic or tumor-suppressive properties in cancer." (PMID 33462379, 2021). "HNF4α, a tumor suppressor of HCC development, directly represses lnc‐APUE transcription." (PMID 33854885, 2021). "Furthermore, HBV-induced HNF4α suppression appears to increase cell proliferation in vitro and contribute to tumor development in nude mouse xenograft models." (PMID 34771521, 2021). "Notably, a subpopulation of these resistant tumours still retains the ability to differentiate, as indicated by the expression of HNF4α, suggesting that cellular differentiation is a plastic process as opposed to one that is unidirectional." (PMID 33179425, 2021). "Furthermore, they demonstrated that the tumor-promoting effect of HNF4α is due to its interaction with anti-apoptotic oncogenes and cytokines." (PMID 34771521, 2021). "Notably, HNF4α expression was also progressively reduced in tumors of the HCC patients with the advancement of the tumor stage in the TCGA LIHC dataset, and lower expression of HNF4α was associated with shorter patient survival." (PMID 32770044, 2020). "Moreover, our results showed that interference of HNF4α significantly impaired HNF3γ’s tumor suppressor function in HCC cells." (PMID 33361765, 2020). "Another factor that drives cytotoxicity of tumor cells is HNF4A." (PMID 32357464, 2020). "Importantly, HNF4α downregulation increased cell proliferation, which contributed to the formation and development of tumor in xenograft nude mice." (PMID 32023898, 2020). "Moreover, the mechanism of HNF4A to confer chemoresistance to Gemcitabine is through (a) direct regulation of hENT1, which is responsible for Gemcitabine uptake of tumor cells." (PMID 32357464, 2020). "This is consistent with the tumor suppressive function of the TSGs regulated by HNF4A." (PMID 32774369, 2020). "As HNF4α suppresses EMT31,34–36, the shared metabolic changes between above two cell types suggest that defective SAA metabolism driven by HNF4α deficiency could be a feature of EMT, which is commonly associated with tumor metastasis and drug resistance." (PMID 32770044, 2020). "Although others have shown that HBx activates signals that can diminish the overall level of HBV replication in order to balance cell survival, in long-term HBV infection, we showed a considerable reduction in HNF4α level attained by HBx to elevate cell proliferation and tumor progress." (PMID 32023898, 2020). "There are contradictory reports on whether HNF4α acts as an oncogene or a tumor suppressor in different cancer models, including CRC." (PMID 33552987, 2020).
tumor (continued). "In addition, the tumor tissues were positive for the hepatocyte-specific marker, HNF4α, which was colocalized in the same cells that had elevated SQSTM1 and UB staining." (PMID 32382012, 2020). "As a tumor suppressor, HNF4A is usually downregulated in tumor samples." (PMID 30547817, 2018). "Interestingly, several studies demonstrated that a reduction in HNF4A activity is highly related to tumor establishment." (PMID 29899848, 2018). "HNF4A plays a role in organ development, wound healing, and tumor progression." (PMID 30547817, 2018). "This in turn leads to tumor progression in the context of decreased HNF4A mRNA expression." (PMID 29899848, 2018). "Furthermore, these data reveal that forced expression of BMAL1 inhibits HNF4α-positive tumor growth." (PMID 30341289, 2018). "A recent study of Yap KO and Mst1/2 double KO mice also demonstrated severe HCC phenotypes with a concomitant reduction in Hnf4a expression, suggesting that the inhibition of mouse Hnf4a activity is an important trigger in tumor formation and/or progression in liver." (PMID 29899848, 2018). "Indeed, the expression of P1- and P2-driven HNF4A was described to be altered in several tumor tissues." (PMID 28648900, 2017). "HNF4A could be a tumor suppressor; indeed, they sought to inhibit it with MEDICA 16, a known drug inhibitor, observing an increase in cell proliferation." (PMID 28912682, 2017). "The protein expression of the tumor suppressor HNF4α may be inhibited by interactions of RBPs with the G4 motif in the 5′ UTR to promote cell proliferation during liver development and carcinogenesis." (PMID 29234104, 2017). "In this study, we used both H1415 and K9218 monoclonal antibodies to detect P1/P2- and P1-promoter-driven HNF4α, respectively, in the liver and tumor samples to determine how the expression of these two isoforms may play a role in SAA1 expression patterns." (PMID 28938650, 2017). "For example, P1-driven HNF4α acts as a tumor suppressor in mouse liver." (PMID 27166517, 2016). "Similarly, many of the strong co-expression patterns existent between the targets of HNF4A and HNF4A itself in normal samples wre also abrogated in tumor samples." (PMID 25961905, 2015). "In particular, HNF4α (as well as other LETFs) was found to directly regulate expression of the liver-specific microRNA-122 (miR-122), the most abundant miRNA in hepatocytes, and the first miRNA suggested as a tumor suppressor in the liver." (PMID 28943628, 2015). "Several lines of evidence indicate HNF4α as a potential tumor suppressor of HCC." (PMID 28943628, 2015). "The lack of correlation between miR-34a and Axl expression levels led us to hypothesize that miR-34a could primarily act through regulation of other target mRNAs, such as the tumor suppressor HNF4A, which is a known target of miR-34a." (PMID 26287733, 2015). "By contrast, loss of HNF4α promotes the expression of EMT genes and tumor progression." (PMID 26157476, 2015). "A recent study by Lucas and colleagues suggest that HNF4A acts as a tumor suppressor." (PMID 23671415, 2013). "Thus, genes targeted by HNF4α in the insulin signaling pathway as well as such related to cell death and tumour suppressor activity were identified." (PMID 21829439, 2011). "This suggests that HNF4α exhibits tumour suppressing functions." (PMID 21244694, 2011). "Collectively then, the summarised findings suggest that impairment of the HNF1β/HNF4α signalling network may lead to tumour formation." (PMID 16479257, 2006). "Furthermore, HNF4α’s dual role—acting as a tumor suppressor in HCC and a contextual oncogene in PDAC—is mediated through its interaction with co-factors such as PGC-1α, FOXA2, and SOX9, as well as epigenetic modifications that affect its chromatin-binding activity." (PMID 40926269, 2025). "Furthermore, the tumor-promoting effects of KDM1A were also attenuated by HNF4A-liver-TE deletion." (PMID 38965210, 2024).
tumor (continued). "However, several other studies claimed that HNF4A functioned as a tumor suppressor in cancers." (PMID 37180584, 2023). "Moreover, HNF4α is known as a key tumor suppressor that inhibits the progression of HCC." (PMID 32023898, 2020). "Indeed, the tumor suppressor function exerted by HNF4α has been demonstrated in HCC." (PMID 31695151, 2020). "Dysregulation of HNF4A mRNA expression may therefore play a role in tumor development." (PMID 29899848, 2018). "Thus, it indicated that Hp infection increases HNF4α expression before the tumor occurs and HNF4α may trigger the final transformation." (PMID 26870992, 2016). "Interestingly, we have recently found that HNF4A is a tumor suppressor gene in HCC pathogenesis." (PMID 26206264, 2015). "This suggests that HNF4α may act as a tumor suppressor in epithelial carcinogenesis." (PMID 22629454, 2012). "Furthermore, several data indicate that HNF4α might act as a tumor suppressor whose inactivation leads to carcinogenesis." (PMID 22140441, 2011). "TF motif enrichment analysis revealed loss of accessibility at sites that contained motifs for epithelial-specifying genes, including HNF4A and CDX2 in patients with HiSquam tumours." (PMID 40468074, 2025). "Collectively, these multilayered HNF4α-centered regulatory networks maintain epithelial identity, suppress dedifferentiation and EMT, and restrain tumor progression." (PMID 41595461, 2025). "Module 8 was implicated in metabolic regulation and immune responses, such as HNF4A and IRF7, and was upregulated in Il1r2−/− tumor cells." (PMID 40767963, 2025). "In these cases, HNF4α and TTF-1 were expressed heterogeneously and were mutually exclusive within the same tumor." (PMID 38710944, 2025). "Some of them heterogeneously expressed HNF4α and TTF-1, which were mutually exclusive within the same tumor." (PMID 38710944, 2025). "In the SOX4-expressing components of the tumor, a subset of cells with higher nuclear β-catenin levels and cholangiocytic markers express FGF19, which promotes proliferation of surrounding HNF4A-expressing hepatoblastic cells." (PMID 39567523, 2024). "The presence of HNF4A+ and LEF1+ tumor clusters was generally consistent with the mixed embryonal and fetal histological classification made by the pathologist (R.R.d.K.)." (PMID 39567475, 2024). "We further validated the expression of EGFR by IF staining, showing EGFR staining primarily in HNF4A+ regions, underscoring the critical role of EGF signaling in fetal tumor cells." (PMID 39567475, 2024). "The overexpression of these oncogenes successfully produces separate regions of HNF4α+;panCK+;CK19− poorly differentiated HCC and HNF4α−;CK19+ CCA, resembling the clinical cHCC-CCA tumor pathology." (PMID 39273023, 2024). "For instance, in some tumor tissues, LEF1+ and HNF4A+ clusters were diffusely intermixed, whereas they were more separated in others." (PMID 39567475, 2024). "Four of the top 5 regulons in stromal or tumor region were overlapped, including CDX1, IRF8, HNF4A, and CREB3lL1." (PMID 38729966, 2024). "We observed distinct regions of HNF4A+ cells and LEF1+ tumor cells, but also LEF1+ clusters that were interspersed with HNF4A+ clusters, as illustrated in PT13." (PMID 39567475, 2024). "ScATAC analysis identified enrichment of TF motifs for hepatic development in the fetal-I and II tumor organoids, such as HNF family members (HNF4A, 4 G, 1B, 1 A), RXRG and PPARD." (PMID 39567475, 2024).